TDRD9 (tudor domain containing 9)
Description:
ATP-binding RNA helicase required during spermatogenesis. Required to repress transposable elements and prevent their mobilization, which is essential for the germline integrity. Acts via the piRNA metabolic process, which mediates the repression of transposable elements during meiosis by forming complexes composed of piRNAs and Piwi proteins and governs the methylation and subsequent repression of transposons. Acts downstream of piRNA biogenesis: exclusively required for transposon silencing in the nucleus, suggesting that it acts as a nuclear effector in the nucleus together with PIWIL4.
Synonyms: C14orf75; DKFZp434N0820; FLJ36164; NET54; HIG-1; HLS; SPGF30; SPNE
Tractability: PROTAC: ubiquitination databases record sites on it.
Gene: Protein-coding gene on chromosome 14 (103,928,456 to 104,052,667, forward strand). Ensembl gene ENSG00000156414.
Subcellular location: Cytoplasm; Nucleus
Pathways (Reactome):
Gene expression (Transcription): PIWI-interacting RNA (piRNA) biogenesis
Gene Ontology:
Molecular function: ATP hydrolysis activity; helicase activity; ATP binding; nucleic acid binding; RNA helicase activity
Biological process: spermatogenesis; fertilization; male meiosis I; male meiotic nuclear division; piRNA processing; transposable element silencing by piRNA-mediated DNA methylation; transposable element silencing by piRNA-mediated heterochromatin formation
Cellular component: cytoplasm; nucleus; piP-body
Genetic constraint (gnomAD): Loss-of-function variants: 87 observed, 116.48 expected, observed/expected ratio (o/e) 0.75, 90% interval 0.63 to 0.89. The upper end of that interval is the gene's LOEUF score, 0.89, which puts it in group 3 of 6, group 1 being the genes least tolerant of losing a copy. Missense variants: 1,168 observed, 1,354.6 expected, observed/expected ratio (o/e) 0.86, 90% interval 0.82 to 0.9. Synonymous variants: 498 observed, 488.89 expected, observed/expected ratio (o/e) 1.02, 90% interval 0.95 to 1.1.
Homologues: Orthologues: chimpanzee TDRD9 (99% identical), macaque TDRD9 (93% identical), dog TDRD9 (88% identical), mouse Tdrd9 (86% identical), rat Tdrd9 (86% identical), guinea pig TDRD9 (85% identical), pig TDRD9 (82% identical), tropical clawed frog tdrd9 (63% identical), rabbit TDRD9 (55% identical), zebrafish tdrd9 (52% identical), Drosophila melanogaster spn-E (31% identical). Paralogues in human: YTHDC2 (19% identical), DHX57 (18% identical), DHX9 (18% identical), DHX29 (18% identical), DHX34 (18% identical), DHX36 (17% identical), DHX30 (16% identical), DHX37 (16% identical), DHX8 (16% identical), DHX16 (15% identical), DHX38 (14% identical), DHX15 (14% identical), and 6 more.